TLR2 (toll like receptor 2)
Diseases named in the same sentence as TLR2 in open-access papers (continued):
Sharing a sentence is not in itself a finding about the gene and the disease.
Mycoplasma infection (4 papers, 2010 to 2022). "One study suggests that mycoplasma infection stimulates mucin production in mice or a human epithelial cell line through interaction with TLR2." (PMID 20505832, 2010). "Together, our findings show that TLR2 recognizes M. pulmonis, and this interaction can promote early cytokine responses and resistance to mycoplasma infection in the respiratory tract." (PMID 20505832, 2010). "Thus, both TLR2-dependent and –independent responses are elicited after mycoplasma infection, and most likely each contribute to the progression of infection and disease." (PMID 20505832, 2010). "In TLR2 knockout (TLR2-/-) mice, the levels of TNF-α in bronchial alveolar lavage fluid (BALF) and peripheral blood after mycoplasma infection and the pathological changes in the lung tissue of mice were detected." (PMID 35372108, 2022). "TLR2/MyD88 signaling induces PGE2 production by COX-2 transcription via NF-κB, during not only Mycoplasma infection but also other bacterial infection such as Mycobacterium bovis, Mycobacterium leprae, and Staphylococcus aureus." (PMID 32154274, 2020). "As lipoproteins from other mycoplasmas can stimulate cells using TLR2, our studies support a role of TLR2, along with TLR1 and/or TLR6, recognition in infection and disease pathogenesis in other mycoplasma infections, including those that affect humans." (PMID 20505832, 2010). "Unlike canonical TLR2 signaling that is triggered in response to the detection of Mycoplasma infection, innate immune activation by components of Mycoplasma-infected cells was inhibited by chloroquine treatment and sensitive to protease treatment." (PMID 26565413, 2015).
myeloma (4 papers, 2015 to 2025). "Several myeloma-derived exosomes activated the IFN-γ production in NK via a mechanism depending on the activation of NF-kB in a TLR2/HSP70-dependent manner." (PMID 40443670, 2025). "For instance, using immunoglobulin E (IgE) producing myeloma (U266 cells), sophorolipids extracted from Candida bombicola decreased IgE and gene expression levels of STAT3, TLR-2, and IL-6." (PMID 36441210, 2023). "TLR2 can recognize different types of deoxyadenosine, including HSP family proteins, and another study recognize that NK cells expressing TLR2 can receive the stimulation of exosomes in multiple myeloma that also confirmed this view." (PMID 34659412, 2021).
neutropenia (4 papers, 2014 to 2025). A decrease in the number of neutrophils found in the blood. "This study highlights the therapeutic potential of targeting TLR2 to alleviate neutropenia and underscores the utility of a multi-omics approach in uncovering drug mechanisms." (PMID 41432050, 2025). "TLR2 and TLR4 mRNA expression was higher in patients with neutropenic fever than in the group with asymptomatic neutropenia after chemotherapy, although the difference was not statistically significant." (PMID 25412934, 2014).
onchocerciasis (4 papers, 2016 to 2022). Onchocerciasis is a form of filariasis, caused by the parasitic worm Onchocerca volvulus, transmitted by the black fly. "In human filarial nematode Onchocerca volvulus infections, NET formations were found around the adult worm containing nodules and the mechanism of NET formation was linked to the presence of Wolbachia and TLR2/651." (PMID 28004792, 2016). "Also, a mechanism of NETosis has been demonstrated in human onchocerciasis with an induction via Wolbachia endobacteria and direct ligation of Wolbachia lipoprotein by neutrophil TLR2/6." (PMID 28486498, 2017). "The filarial endosymbiont Wolbachia is known to elicit immune responses through TLR2 and TLR4 and is known to be the major mediator of inflammatory responses in lymphatic filariasis and onchocerciasis." (PMID 29225962, 2017). "TLR2 and TLR6 are of particular importance, as filariae including the causative agents of LF, onchocerciasis and mansonellosis, but not loiasis, contain endosymbiotic Wolbachia bacteria, which trigger an inflammatory response through TLR2 and TLR6 recognition." (PMID 36389745, 2022). "TLR2 is a receptor that plays an important role in filarial infection; the filarial endosymbiont Wolbachia is known to elicit immune responses through TLR2 and TLR4 and is known to be the major mediator of inflammatory responses in lymphatic filariasis and onchocerciasis." (PMID 29225962, 2017).
osteoporosis (4 papers, 2022 to 2026). A condition of reduced bone mass, with decreased cortical thickness and a decrease in the number and size of the trabeculae of cancellous bone (but normal chemical composition), resulting in increased fracture incidence. "Collectively, P. gingivalis acts as a keystone pathogen driving the initiation and progression of periodontitis-associated osteoporosis, while F. alocis functions as an important contributing pathogen that synergizes with P. gingivalis and directly induces bone loss through TLR2-mediated pathways." (PMID 41551989, 2026). "TLR2, expressed in dendritic cells and involved in bone metabolism through the mechanism of osteoimmunology, is critical for osteoporosis management, as its activation inhibits inflammatory osteoclast differentiation and mitigates bone loss." (PMID 41403949, 2025). "In addition inhibition of TLR2 may suppress osteoclastic bone resorption, thereby improving osteoporosis." (PMID 36034791, 2022). "Nevertheless, its contribution to osteoporosis is non-negligible: EVs derived from F. alocis induces the production of proinflammatory cytokines (IL-6 and TNF-α), promotes osteoclastogenesis, and triggers systemic bone loss through TLR2 signaling." (PMID 41551989, 2026).
pancreatic adenocarcinoma (4 papers, 2019 to 2024). "Because Toll-like receptor 2 (TLR2) is broadly expressed among many cancer types including pancreatic adenocarcinomas, a high-affinity TLR2-targeted fluorescence molecular imaging agent (TLR2L-800) was developed." (PMID 39320054, 2024). "Human TLR2 is broadly expressed among pancreatic adenocarcinomas, and the highly specific TLR2L-800 fluorescence molecular imaging agent has potential for use in fluorescence-guided surgery to increase R0 margins and improve patient survival." (PMID 39320054, 2024). "Lipopolysaccharide (LPS) can bind to the Toll-like (TLR) receptors; TLR2, TLR4, and TLR9 are associated with pancreatic adenocarcinoma development." (PMID 32344895, 2020). "In addition, TLR2, TLR4, and TLR9 and the downstream target of TLR4, MyD88, are associated with pancreatic adenocarcinoma development." (PMID 32344895, 2020). "We and others have reported that Toll-like receptor 2 (TLR2) is broadly expressed among many cancer types and has particularly broad and high expression among pancreatic adenocarcinomas." (PMID 39320054, 2024).
pancreatic ductal adenocarcinoma (4 papers, 2018 to 2026). An infiltrating adenocarcinoma that arises from the epithelial cells of the pancreas. "Previous studies demonstrated that, in pancreatic ductal adenocarcinoma, TLR2 and TLR4 serve as positive predictors of prognosis in stage I and II disease and in patients with small-size tumors." (PMID 32424768, 2020). "However, blocking TLR2 did not reduce P. gingivalis-induced PDAC cell proliferation, as Pancreatic ductal adenocarcinoma cell lines do not express TLR2." (PMID 39872848, 2024).
paracoccidioidomycosis (4 papers, 2012 to 2024). A systemic fungal infection caused by Paracoccidioides brasiliensis that is most often seen in immunocompromised patients. "Indeed, our previous studies with C57BL/6 TLR2 deficient mice demonstrated that inflammatory PMNs induced by enhanced Th17 immunity are protective in paracoccidioidomycosis." (PMID 23226464, 2012). "Our previous studies in murine paracoccidioidomycosis have shown that the expansion of IL-17 producing cells is controlled by several pathogen recognition receptors (TLR-2, TLR-4, dectin-1) as well as the IL-1R and Toll adaptor protein, MyD88." (PMID 25411790, 2014). "In TLR-2−/− mouse studies, the role of TLR-2 in paracoccidioidomycosis was less clear." (PMID 32545735, 2020).
pneumonitis (4 papers, 2012 to 2018). An inflammatory process affecting the lung parenchyma. "For the C57BL/6J and Tlr2,4−/− strains, all mice presenting respiratory distress were confirmed to have developed significant pneumonitis (average score = 4.3), compared to the level in untreated control mice (average score = 0.5)." (PMID 28912510, 2017). "In TLR2 -/- KO mice infected with mouse pneumonitis (MoPn), decreased fibrosis and inflammation with in oviducts and mesosalpinx correlated with abated IL-6 concentrations." (PMID 22894815, 2012). "The pneumonitis and fibrosis scores increased in mice of the Tlr2,4−/− strain at 20 weeks and no mice of this strain survived to the later timepoints." (PMID 28912510, 2017).
preeclampsia (4 papers, 2013 to 2022). Preeclampsia is a hypertensive disorder of pregnancy that is characterized by new-onset hypertension with proteinuria presenting after 20 weeks of gestation, and depending on mild or severe forms may initially present with severe headache, visual disturbances, and hyperreflexia. "Another factor, which is predisposed to preeclampsia, is the genetics of TLR2 and TLR4 polymorphism." (PMID 32508811, 2020). "Previous studies have also identified immune-system alterations associated with the origin of preeclampsia as well as genetic associations between TLRs and preeclampsia: TLR2 and TLR4 SNPs appear to alter susceptibility to developing preeclampsia." (PMID 26089598, 2015). "To confirm the presence of vital NETosis in normal pregnancy and in pregnancy complicated by preeclampsia, we performed experiments using anti-TLR2 and anti-TLR4 blocking antibodies." (PMID 36684420, 2022). "Single nucleotide polymorphisms in TLR2 (Arg753Gln) and TLR4 (Asp299Gly/Thr399Ile) have been associated with early onset of preeclampsia, with an exception in the Caucasian population." (PMID 32508811, 2020). "The screening of common TLR2 (2258 G>A) and co-segregating TLR4 (1063A>G and 1363C>T) SNPs in 94 women with preeclampsia and 176 healthy pregnancy controls showed the associations of these SNPs with early-onset but not late-onset preeclampsia." (PMID 23161283, 2013).
rectal cancer (4 papers, 2014 to 2024). A primary or metastatic malignant neoplasm that affects the rectum. "Several cytokines, including interleukins and interferons, and other mediators of inflammation were associated with both colon (INFGR1, IL6, IRF2, NFκB1A, TLR2) and rectal cancer survival (IL1A and IL3), as was suppressor of cytokine signaling (SOCS1)." (PMID 25541970, 2014).
scleroderma (4 papers, 2019 to 2021). Scleroderma is a rare autoimmune connective tissue disorder characterized by abnormal hardening of the skin and, sometimes, other organs. "Moreover, studies in a scleroderma model demonstrate stimulation of B cells with the ECM component hyaluronan activates TLR2 and TLR4 and results in inflammatory cytokine secretion, including IL-6, TNFα, and IFNγ." (PMID 34381449, 2021). "Therefore, we quantified the numbers of M2 macrophages, which include CD68+CD163+ or CD68+Arginase-I+ populations, and M1 macrophages including CD68+NOS2+ and CD68+TLR2+ populations in scleroderma skin." (PMID 31552041, 2019). "The number of M1 macrophages, which include CD68+TLR2+ and CD68+NOS2+ cells, were increased in BLM-treated scleroderma skin, and EchA co-treatment reduced the number of M1 macrophages." (PMID 33922418, 2021). "Moreover, CIC activate TLR2, TLR3 and TLR4 in scleroderma, again resulting in two synergistic pairings, TLR2-TLR4 and TLR3-TLR4, that can continue to drive chronic inflammation." (PMID 32629865, 2020). "Moreover, the numbers of M1 macrophages including CD68+NOS2+ and CD68+TLR2+ populations increased in BLM-induced scleroderma skin; however, the BLM-induced increase of M1 macrophage (CD68+NOS2+ and CD68+TLR2+) populations was not significantly affected by WKYMVm treatment." (PMID 31552041, 2019).
scrapie (4 papers, 2011 to 2022). A fatal disease of the nervous system in sheep and goats, characterized by pruritus, debility, and locomotor incoordination. "To assess the influence of these individual innate immune receptors on CNS prion pathogenesis, we used ic inoculation of 22L scrapie in mice deficient in TLR2 (Tlr2-/-), C3aR1 (C3ar1-/-), or C5aR1 (C5ar1-/-)." (PMID 30596651, 2018). "Remarkably, contrasting expression patterns were found in the hippocampus of the scrapie-infected sheep, in which TLR2 and MyD88 were downregulated (p < 0.01) and TLR1 showed a tendency towards downregulation (p < 0.1)." (PMID 35408945, 2022). "In the thalamus, TLR6, MyD88, and CD36 were significantly upregulated in the scrapie-infected group (p < 0.05), while TLR2 and TLR3 displayed a tendency towards upregulation (p < 0.1)." (PMID 35408945, 2022). "Our study clearly shows that TLRs, and especially TLR4 in sheep and TLR1 and TLR2 in mice, are involved in the pathogenesis of scrapie." (PMID 35408945, 2022). "In this region, the expression of TLR2, 3, 4, 6, 7, 8, 9, and CD36 was significantly higher (p < 0.01) in the scrapie-infected versus control animals." (PMID 35408945, 2022). "Our findings in the hippocampus of scrapie-infected sheep reveal an opposite pattern compared with other analyzed brain areas, with the downregulation of TLR1, TLR2, and MyD88 and no cytokine alterations." (PMID 35408945, 2022).
Spondyloarthritis (4 papers, 2010 to 2026). "The polymorphism rs5743708 for the TLR2 and the rs187084_rs5743836 TLR9 haplotypes appear to be involved in the development of clinical forms of SpA and can be a possible therapeutic target for the spondyloarthritis." (PMID 31781672, 2019). "In addition, De Rijcke and colleagues showed that anti-TNF treatment in spondylarthropathy results in a reduced expression of TLR2 and TLR4." (PMID 21179534, 2010).
squamous carcinoma (4 papers, 2018 to 2024). "TLR2 stimulates extracellular signal‐regulated kinases 1/2 to enhance the development of human squamous carcinoma cells." (PMID 38685971, 2024). "Another study showed that stimulation of TLR2 promotes TLR2 positive squamous carcinoma cell growth." (PMID 33898309, 2021). "TLR2 is expressed on keratin‐forming cells of dysplastic epithelia and squamous carcinoma, whereas TLR2 expression in malignant keratinized cells may be associated with apoptosis resistance." (PMID 38685971, 2024). "Summarizing the Results section, significant differences were observed in the expression of various TLRs (TLR-2, TLR-3, TLR-4, TLR-7, TLR-8, and TLR-9) on selected T and B cell subpopulations between the patients with squamous cell carcinoma (SCC) and the healthy controls." (PMID 39124797, 2024). "We conclude that TLR2 and adenosine receptor agonists, known to be present in the tumor microenvironment, may contribute to OSCC progression in part via direct effects on the ERK1/2 pathway in squamous carcinoma cells." (PMID 29467931, 2018).
syphilis (4 papers, 2014 to 2024). A contagious bacterial infection caused by the spirochete Treponema pallidum. "For instance, in 456 Caucasian syphilis patients, polymorphisms in the T>G +1805 (TLR1), G>A +2258 (TLR2), and C>T +745 (TLR6) were looked for." (PMID 37937275, 2023). "The findings implied that Arg753Gln (TLR2) does protect against syphilis development." (PMID 37937275, 2023). "Syphilis is caused by the bacterium Treponema pallidum, and the infection has up-regulated the human Micro RNA (miR-101-3p) that paired with the 3’ UTR of mRNA of the TLR2 gene to downregulate the TLR2 gene expression and eventually reduced the cytokine secretion." (PMID 39729468, 2024).
abortion (3 papers, 2018 to 2025). the ending of pregnancy by removing a fetus or embryo before it can survive outside the uterus. "Next factors that can also be considered when predicting the risk of spontaneous abortion are SNPs in TLR2, TLR4, IL-6, IL-8, and PGR genes." (PMID 30116270, 2018). "However, an association between disturbed TLR4 and TLR2 expression on spermatozoa with unexplained recurrent spontaneous abortion (URSA) has been determined." (PMID 36504703, 2023). "We have included three important and different in function Toll-like receptors (TLR2, TLR4, and TLR9) to study the relation between TLR SNPs and risk of spontaneous abortion." (PMID 30116270, 2018). "This suggests that reduced TLR2/4 expression may mitigate bacterial infection–induced damage to sperm, potentially serving as a protective mechanism in abortion‐prone environments." (PMID 40242391, 2025). "Interestingly, in cases of unexplained recurrent spontaneous abortion (URSA) in humans, sperm from affected patients exhibit lower TLR2 and TLR4 expression than sperm from fertile individuals." (PMID 40242391, 2025).
acute monocytic leukemia (3 papers, 2014 to 2019). Acute monoblastic leukemia (AML-M5), is one of the most common subtypes of acute myeloid leukemia (AML) that is either comprised of more than 80% of monoblasts (AML-M5a) or 30-80% monoblasts with (pro)monocytic differentiation (AML-M5b). "As monocytes express high levels of membrane TLR2 and also produce sTLR2, we initially examined the release of sTLR2 into culture supernatant of the acute monocytic leukemia-derived cell line, THP-1, by ELISA." (PMID 25531754, 2014).
acute pancreatitis (3 papers, 2015 to 2025). An acute inflammatory process that leads to necrosis of the pancreatic parenchyma. "Another therapeutic approach was the administration of lornoxicam in acute pancreatitis patients, who presented reduced mortality associated with reduced TLR2 and TLR4 mRNA levels in the peripheral blood mononuclear cells." (PMID 26347203, 2015). "Use of PPAR-α agonist reduced inflammation and severity in acute pancreatitis via repression of TLR2 and TLR4 mRNA." (PMID 26347203, 2015). "It has been shown that T. cruzi can activate NF-kB through Toll-like receptor 2 (TLR2) via GPI–anchored mucin-like glycoproteins on the parasite’s surface, suggesting that acute pancreatitis could begin before the parasite enters the cell." (PMID 40423352, 2025).
allergic contact dermatitis (3 papers, 2012 to 2021). An inflammatory skin condition caused by an immune response to direct contact between the skin and an allergen. "Similar to NLRP12, TLR2 has been shown to be an essential mediator of the immune response to oxazolone (OX) in an allergic contact dermatitis model." (PMID 22291998, 2012).
alveolitis (3 papers, 2013 to 2021). "Analysis of the BAL from individual mice demonstrated that following a single exposure to SR, there is an increase in alveolitis in the WT mice which is significantly reduced in the TLR2/9-/- mice." (PMID 24023674, 2013). "The reduction in alveolitis in the TLR2/9-/- mice correlated with the decrease in neutrophil recruitment that was observed compared to WT mice." (PMID 24023674, 2013). "However, the composition of the alveolitis in TLR2/9-/- mice is different with a significant reduction of neutrophil frequency compared to the WT group." (PMID 24023674, 2013). "Although the TLR2-/- mice, (and to a lesser extent the TLR9-/- mice), had reduced alveolitis compared to the WT mice, the differences were not statistically significant." (PMID 24023674, 2013).
amyloidosis (3 papers, 2016 to 2025). A disorder characterized by the localized or diffuse accumulation of amyloid protein in various anatomic sites. "Certain polymorphisms in the innate immune system genes, SAA and TLR2, were shown to be linked to the development of amyloidosis." (PMID 40218163, 2025). "SAA receptors, such as SELS (glucose homeostasis and ER stress), ABCA1, ABCA7, SCARB1 (cholesterol efflux), CD36, TLR2, TLR4, CST3 (inflammatory signaling), FPR2 (chemotaxis and immune cell activation), and AGER (amyloidosis), have been reported previously." (PMID 27799725, 2016).